GALNT7 (polypeptide N-acetylgalactosaminyltransferase 7)
Diseases named in the same sentence as GALNT7 in open-access papers (continued):
Sharing a sentence is not in itself a finding about the gene and the disease.
colorectal cancer (continued). "The inverse relationship between GALNT7 and PD-L1 was further supported by in vitro experiments, in which GALNT7 depletion resulted in increased PD-L1 levels in at least two MSI colorectal cancer cell lines." (PMID 40824763, 2025). "SNHG7, whose high expression was correlated with poor prognosis, acted as a target of miR-34a to increase GALNT7 level and regulate PI3K/Akt/mTOR pathway in colorectal cancer progression." (PMID 31164492, 2019). "We next conducted survival analysis, and GALNT7-High colorectal cancers showed a nonsignificant trend toward favorable RFS compared with GALNT7-Low colorectal cancers (n = 453; P = 0.0692; HR = 0.57; 95% CI, 0.29–1.02)." (PMID 40824763, 2025). "Among the five genes, GALNT7 expression was robustly associated with favorable prognosis in four independent transcriptomic and IHC cohorts of dMMR/MSI colorectal cancers while showing little or no prognostic impact in pMMR/MSS colorectal cancers." (PMID 40824763, 2025). "Functional assays and lectin microarray analysis using MSI colorectal cancer cell lines revealed that GALNT7 knockdown enhanced IFNγ-induced PD-L1 expression without altering cell-surface glycosylation." (PMID 40824763, 2025). "In contrast, GALNT7 expression did not significantly change during tumor progression from adenoma to stage 0 to IV colorectal cancers." (PMID 40824763, 2025). "However, in this study, GALNT7 knockdown in dMMR/MSI colorectal cancer cell lines did not alter Tn antigen–binding lectin signals or cell-surface Tn antigen expression." (PMID 40824763, 2025). "This analysis identified five glycosyltransferase genes, namely, ST6GAL1, GALNT6, HPSE, GALNT1, and GALNT7, expression of which was consistently upregulated or downregulated in MSI colorectal cancer tissues, cell lines, and single epithelial cells compared with MSS colorectal cancers." (PMID 40824763, 2025). "The same miRNA has also been studied by other researchers, who revealed a CCDC144NL-AS1/miR-363-3p/GALNT7 axis as a driver of CRC cell proliferation and suggested that targeting this lncRNA-mediated circuit may offer a therapeutic strategy in colorectal cancer." (PMID 40871106, 2025). "Collectively, these findings indicate that GALNT7 depletion does not significantly alter cell proliferation, cell-surface glycan profiles, or Tn antigen expression in MSI colorectal cancer cells." (PMID 40824763, 2025). "The GALNT7 H-score was significantly higher in dMMR/MSI colorectal cancers compared with both nontumor mucosa and pMMR/MSS colorectal cancers." (PMID 40824763, 2025). "Upon observing a positive correlation between SNHG7 and GALNT7 and a negative correlation between SNHG7 and miR-34a in colorectal cancer lines." (PMID 33546468, 2021). "Furthermore, using the CPTAC cohort, we confirmed a negative correlation between GALNT7 protein levels and CD274 expression, specifically in MSI colorectal cancers." (PMID 40824763, 2025). "Fourth, we found that GALNT7 had a strong prognostic impact in dMMR/MSI colorectal cancers at both the mRNA and protein levels, whereas it had little or no prognostic value in pMMR/MSS colorectal cancers." (PMID 40824763, 2025). "Notably, GALNT7 expression was inversely correlated with PD-L1 expression at both the mRNA and protein levels in multiple datasets exclusively within dMMR/MSI colorectal cancers, but not in pMMR/MSS CRCs." (PMID 40824763, 2025). "Although GALNT7 was not directly responsible for the regulation of Tn antigen at least in vitro, the dysregulation of multiple GALNT isoenzymes may contribute to aberrant Tn antigen synthesis in dMMR/MSI colorectal cancer cells." (PMID 40824763, 2025).
melanoma (16 papers, 2012 to 2025). A malignant, usually aggressive tumor composed of atypical, neoplastic melanocytes. "Intriguingly, in melanoma cells, GALNT7 silencing was associated with increased IL-10 secretion, enhanced CTLA-4 expression, and the modulation of immune evasion." (PMID 40824763, 2025). "In melanoma, it is related to increased cell invasion due to increased aberrant glycosylations associated with its molecular target GALNT7." (PMID 33562431, 2021). "miR-30d has been previously reported to reduce expression of the Golgi GalNAc transferase GALNT7, affecting O-glycosylation and promoting invasion and metastasis of melanoma cells." (PMID 32770028, 2020). "The suppression of GALNT7 with upregulation of miR-30d increases the secretion of IL-10, providing a possible mechanistic explanation for the immunosuppressive behavior of melanomas." (PMID 27322213, 2016). "During melanoma progression, the expression of GALNT7 is decreased by miR-30b/30d, which promotes cell invasion and immunosuppression by altering the O-glycosylation patterns of membrane proteins interacting with the ECM and cells of the tumor environment." (PMID 27322213, 2016). "Up-regulation of miR-30d or silencing of GALNT7 has significant effects on the O-glycosylation of melanomas." (PMID 27322213, 2016). "Indeed, in prostate cancer and melanoma cells, GALNT7 depletion resulted in decreased Tn antigen levels, as demonstrated by lectin microarray and flow cytometry analyses." (PMID 40824763, 2025). "The ectopic expression of miR-30b/30d has been reported to promote the metastasis of melanoma cells by directly targeting GALNT7 along with increasing the synthesis of immunosuppressive cytokine IL-10 while reducing the activation and recruitment of immune cells." (PMID 34819077, 2021). "Recent study revealed that inhibiting the expression of GALNT7 in melanoma cells could decrease synthesis of immunosuppressive cytokine IL-10 and enhance immune cell activation and recruitment." (PMID 32308562, 2020). "This can be partially associated with increased IL-10 secretion, thus the miR-30b/30d-GALNT7-IL-10 axis could be an explanation of the immunosuppressive behavior of melanoma." (PMID 30866509, 2019). "Moreover, during melanoma progression, the upregulation of miR-30d expression together with the reduced expression of GALNT7 enhances the secretion of IL-10 (interleukin 10) and decreases immune cell activation and recruitment." (PMID 30866509, 2019). "Superficial spreading melanoma (SSM) and nodular melanoma (NM characteristically express the eight genes GALNT7, DIS3, FGFR1OP, G3BP2, MTAP, SEC23IP, USO1, and ZNF668." (PMID 27322213, 2016). "In human melanoma, miR-30b overexpression corresponded with increased metastasis, tumor thickness and advancing stage (I to III), it also plays a crucial role on tumor cell invasion and immune modulation, predominantly by suppressing GALNT7." (PMID 32420372, 2020).
prostate carcinoma (11 papers, 2016 to 2025). A carcinoma that arises from epithelial cells of the prostate gland. "We show GALNT7 can identify men with prostate cancer, using urine and blood samples, with improved diagnostic accuracy than serum PSA alone." (PMID 36725887, 2023). "Targeting aberrant glycosylation holds huge potential for cancer research, and we envisage that both GALNT7, and its associated glycans (particularly the cancer-associated Tn antigen) hold huge promise in prostate cancer therapy that needs to be explored." (PMID 36725887, 2023). "Validation at the protein level confirmed that upregulation of GALNT7 in prostate cancer cells promotes loss of FOXO1 protein." (PMID 36725887, 2023). "Based on this, we hypothesised that upregulation of GALNT7 in prostate cancer cells would alter O-linked glycosylation, including exposure of truncated O-glycans such as the cancer-associated Tn antigen." (PMID 36725887, 2023). "As GALNT7 initiates O-glycosylation to produce the Tn antigen, upregulation of this enzyme could potentially be linked to a range of changes in O-glycans in prostate cancer cells." (PMID 27428423, 2016). "It has been reported that GALNT7 affects prognosis in several cancers, including prostate cancer, breast cancer, and glioma." (PMID 40844495, 2025). "Based on these findings, we propose GALNT7 is a key player in prostate cancer that can likely be exploited for therapeutic usage." (PMID 36725887, 2023). "Our findings identify GALNT7 as an important driver of prostate cancer progression, and highlight new opportunities to exploit aberrant O-glycosylation to improve diagnosis and treatment." (PMID 36725887, 2023). "We previously reported preliminary findings suggesting that GALNT7 gene levels are upregulated in clinical prostate cancer tissue, compared to normal or benign prostate tissue." (PMID 36725887, 2023). "Mechanistically, GALNT7 can modify O-glycosylation in prostate cancer cells and correlates with cell cycle and immune signalling pathways." (PMID 36725887, 2023). "As over 80% of the secretome is O-glycosylated, we predicted that upregulation of GALNT7 will also alter the secretome of prostate cancer cells." (PMID 36725887, 2023). "Here, we demonstrate using multiple independent clinical cohorts that the glycosyltransferase enzyme GALNT7 is upregulated in prostate cancer tissue." (PMID 36725887, 2023). "Next, we validated DBNDD1 expression in GSE220942 (the role of GALNT7 upregulation in PCa cells) and GSE217260 (DEGs of benign prostatic hyperplasia and high-risk prostatic carcinoma tissues)." (PMID 37569304, 2023). "Our study provides a new biomarker to aid the diagnosis of clinically significant disease and cements GALNT7-mediated O-glycosylation as an important driver of prostate cancer progression." (PMID 36725887, 2023). "To test if upregulation of GALNT7 can alter the cell surface O-glycosylation of prostate cancer cells, we created and validated stable prostate cancer cell line models with knockdown or up-regulation of GALNT7 and assessed the recognition by lectins." (PMID 36725887, 2023). "For example, N-Acetylgalactosaminyltransferase 7 (GALNT7) is upregulated in prostate cancer (PRAD) and can promote its proliferation by modifying the O-glycosylation of PRAD cells." (PMID 37894512, 2023). "In this study, we measured levels of the glycosylation enzyme GALNT7 in prostate cancer tissue, urine and blood samples and identified GALNT7 as being significantly upregulated in prostate cancer." (PMID 36725887, 2023). "We noted that the localisation of both proteins in prostate cancer tissue was similar, which was unexpected because GALNT7 is a Golgi-resident enzyme in healthy cells while PSA is secreted into blood." (PMID 36725887, 2023). "To identify signalling pathways controlled by GALNT7 in prostate cancer cells, we used RNA-sequencing to search for genes that change with either knockdown or upregulation of GALNT7." (PMID 36725887, 2023).
prostate carcinoma (continued). "Here, we demonstrate urine GALNT7 can identify men with prostate cancer with improved accuracy than serum PSA levels, and show that combining GALNT7 with PSA further improves diagnostic performance." (PMID 36725887, 2023). "Next, we analysed the O-glycoproteome in secretomes of DU145 prostate cancer cells with upregulated GALNT7 using mass spectrometry." (PMID 36725887, 2023). "Here, we equipped cells with the ability to tag protein substrates of GALNT7 and report GALNT7 dependent glycosylation of secreted proteins in living prostate cancer cells." (PMID 36725887, 2023). "GALNT7 protein levels were 2.2 fold higher in men with prostate cancer compared to men diagnosed with benign disease (p < 0.0001)." (PMID 36725887, 2023). "Next, to gain insight into how GALNT7 is expressed during prostate cancer progression, we analysed GALNT7 in a TMA with hormone sensitive and CRPC patients (n = 125)." (PMID 36725887, 2023). "First, we monitored GALNT7 in matched urine and plasma samples from 27 men with suspected prostate cancer." (PMID 36725887, 2023). "In line with this, one study showed androgen-regulated glycosylation by GALNT7 as an important modification for the viability of prostate carcinoma cells." (PMID 37671061, 2023). "Consistent with this, our findings indicate GALNT7 correlates with immune signalling pathways in prostate cancer." (PMID 36725887, 2023). "Our findings reveal urine GALNT7 can identify men with prostate cancer with improved accuracy compared to serum PSA levels, and show combining GALNT7 with serum PSA further improves diagnostic performance." (PMID 36725887, 2023). "We next investigated the effects of GALNT7 on the biology of prostate cancer cells showing that knockdown of GALNT7 inhibits prostate cancer cell proliferation and colony formation in vitro, whereas overexpression of GALNT7 has the opposite effect." (PMID 36725887, 2023). "We previously showed that expression of GALNT7 is controlled by the AR and that GALNT7 is upregulated in prostate cancer cells in response to androgen stimulation." (PMID 36725887, 2023). "This identified 34 glycopeptides as potential substrates for the GALNT7 enzyme in prostate cancer cells, the Tn antigen being the most abundant O-glycosylated form." (PMID 36725887, 2023). "Here, we analyse multiple independent cohorts of patient tissue samples and find upregulation of GALNT7 is a feature of prostate cancer cells." (PMID 36725887, 2023). "Next, we monitored GALNT7 plasma levels in 305 men diagnosed with either benign disease or prostate cancer." (PMID 36725887, 2023). "Using the BH-GALNT7 reporter, we report specifically GALNT7 dependent glycosylation of secreted proteins in prostate cancer cells." (PMID 36725887, 2023). "Using quantitative PCR, we further show upregulation of the GALNT7 gene in prostate cancer tissue in two additional primary patient cohorts." (PMID 36725887, 2023). "GALNT7 urine levels were also monitored in 180 men with suspected prostate cancer taking part in the INNOVATE clinical trial." (PMID 36725887, 2023). "In this study we confirm androgen regulation of ST6GalNAc1 and show for the first time a link between androgens and two additional O-glycosylation enzymes in prostate cancer, GALNT7 and GCNT1." (PMID 27428423, 2016). "Moreover, prostate cancer tissues and cell lines with decreased GALNT7 expression exhibited significant enrichment of immune-related pathways, such as immunoregulatory interaction and IFNγ response." (PMID 40824763, 2025). "Using pre-validated sandwich ELISA assays, we tested GALNT7 protein levels in urine and blood samples from men with suspected prostate cancer (our power calculations showed testing at least 20 samples would give us a 90% chance of detecting any significant changes, p < 0.05)." (PMID 36725887, 2023).
prostate carcinoma (continued). "Taken together, our findings reveal that in prostate cancer cells, GALNT7 can modify the O-glycosylation of both cell surface proteins and proteins in the secretory pathway, leading to upregulation of the Tn antigen, which is a hallmark of cancer and involved in tumor progression and metastasis." (PMID 36725887, 2023). "Furthermore, we show GALNT7 is found in diagnostically relevant levels in the urine and blood of men with prostate cancer." (PMID 36725887, 2023). "By analysing tumour and blood samples from men with prostate cancer, we further show that GALNT7 levels remain high in castrate resistant prostate cancer, thus suggesting GALNT7 is increased during both the development of prostate cancer and the progression to relapsed treatment resistant disease." (PMID 36725887, 2023). "Furthermore, using in vitro assays we show GALNT7 promotes prostate cancer cell migration and invasion." (PMID 36725887, 2023). "Based on this, and because shedding of glycosylatransferases has been previously reported, we hypothesised that like PSA, GALNT7 may also be secreted into the urine and blood of men with prostate cancer." (PMID 36725887, 2023). "Urine GALNT7 had slightly improved accuracy over serum PSA at identifying men with prostate cancer within the same cohort (serum PSA: AUC 0.69, urine GALNT7: AUC 0.73), whereas combining PSA and GALNT7 further increased diagnostic accuracy (PSA + GALNT7: AUC 0.76)." (PMID 36725887, 2023). "Furthermore, staining of a TMA containing matched normal and prostate cancer tissue from 200 patients showed GALNT7 levels were 1.8 fold higher in prostate cancer tissue compared to matched normal tissue from the same patient (p < 0.001)." (PMID 36725887, 2023). "Here, we monitor GALNT7 at both the gene and protein level in multiple independent patient cohorts (comprising >2000 patient samples) and establish upregulation of GALNT7 as a feature of prostate cancer." (PMID 36725887, 2023). "The data presented indicates upregulation of GALNT7 may increase the expression of the Tn antigen in prostate cancer." (PMID 36725887, 2023). "Based on these data, we propose that GALNT7 is upregulated in prostate cancer and could be developed further as a as a non-invasive diagnostic biomarker." (PMID 36725887, 2023). "It is tempting to speculate that the enhancement of prostate cancer cell proliferation by GALNT7 is likely due to either the activity of secreted GALNT7, or some of its protein substrates’ roles or combined functions." (PMID 36725887, 2023). "Similarly, analysis of a TMA containing 17 normal prostate tissue samples and 79 samples of prostate tumour tissue showed GALNT7 is 2.3 fold upregulated in prostate cancer (p = 0.0124)." (PMID 36725887, 2023). "Taken together, our findings show that GALNT7 is upregulated in the urine and blood of men with prostate cancer and could aid in diagnosis." (PMID 36725887, 2023). "Moving forward, we anticipate the development of both isozyme and pan-specific modulators targeting GALNT7 will yield new inhibitors, conceptually related to the widespread use of drugs targeting protein kinases, to provide a new class of therapeutics to treat prostate cancer." (PMID 36725887, 2023). "Recently, GALNT7 was identified as a single gene effector of cell surface glycosylation and glycocalyx height, suggesting that GALNT7 mediated O-glycosylation might act at the interface of cellular signalling processes in prostate cancer and play an important role in disease progression." (PMID 36725887, 2023). "Our findings also show GALNT7 can modify the O-glycosylation of both cell surface proteins and proteins in the secretory pathway, and identify GALNT7 as a key driver of tumour growth which correlates with cell cycle and immune signalling pathways in prostate cancer cells." (PMID 36725887, 2023).